ELN (elastin)
Diseases named in the same sentence as ELN in open-access papers (continued):
Sharing a sentence is not in itself a finding about the gene and the disease.
emphysema (continued). "Haploinsufficiency at the elastin locus may predispose WBS subjects to premature development of pulmonary emphysema." (PMID 34073948, 2021). "The compromised structural integrity caused by the early stage elastin dysfunction could play a major role in the breakdown of epithelial repair mechanisms, resulting hemorrhage and the gradual development of emphysema." (PMID 32586004, 2020). "In smokers with COPD, elastin degradation in the skin is associated with emphysema severity and carotid pulse wave velocity, indicating that systemic elastin breakdown may be increased in susceptible individuals and not confined to the lung alone." (PMID 31234847, 2019). "MMPs released from macrophages lead to the destruction of elastin and cause emphysema." (PMID 30781876, 2019). "In addition, products of activated leukocytes including MMP-12 and NE can cause destruction of elastin fibres and other components of the interalveolar septum adjacent to these small airways, leading to centrilobular emphysema." (PMID 27046438, 2016). "Changes in major lung ECM components, such as types I and III collagen and elastin could interfere with the mechanical properties of the lung; it is believed that these changes are involved in the loss of elasticity during emphysema progression." (PMID 26052708, 2015). "Nonetheless, the broader physiological implications of elastin-reactive T cells remain undefined and could be explored as a novel diagnostic tool to identify ever-smokers with emphysema." (PMID 22969766, 2012). "However, animal experiments showed that the initial loss was rapidly followed by elastin re-synthesis as the emphysema developed." (PMID 18271964, 2008). "Furthermore, proteolytic destruction in the lungs may lead to loss of elastin and the development of emphysema, which is associated with poor lung function in COPD patients." (PMID 36835197, 2023). "This predisposition to emphysema was proposed to result from a lower availability of cross-linked elastin leading to degradation of the larger elastin fibers, and changes in the adult ECM leading to an increase in collagen that may ultimately prevent matrix remodeling by restricting cell movement." (PMID 34901011, 2021). "Notably, anti-elastin antibodies are also associated with disease parameters, but in contrast to all autoantibodies mentioned earlier, in the opposite direction where a lower antibody titer was associated with more severe disease and emphysema." (PMID 29422903, 2018). "Second, while a single dose of IT PPE causes protease-antiprotease imbalance and associated elastin destruction, inflammation and panacinar emphysema in the murine lung, many other factors are likely implicated in the pathogenesis of chronic smoking-related emphysema in humans." (PMID 27408904, 2016). "Proteases lead to an imbalance with anti-proteases and destroy elastin, the connective tissue in the lung parenchyma, resulting in emphysema." (PMID 41599784, 2026). "These enzymes are synthesized in response to lung irritants like tobacco smoke and result in the generation of elastin peptide fragments that are critical mediators of inflammation in pulmonary emphysema." (PMID 40141701, 2025). "These measurements translate real-time elastin turnover, allowing an early detection and/or monitoring of therapeutic efficacy of emphysema in both clinical and experimental settings." (PMID 41007683, 2025). "Early investigations conducted in the 1970s began to elucidate the connection between elastin degradation and the pathophysiology of emphysema." (PMID 40141701, 2025). "The degradation of elastic fibers is a fundamental characteristic of pulmonary emphysema, resulting in the release of proinflammatory elastin peptides." (PMID 40141701, 2025).
emphysema (continued). "Additionally, elucidating the relationship between localized alveolar wall alterations and the loss of elastin crosslinks in postmortem lung specimens may shed light on the patterns of disease progression in pulmonary emphysema, ultimately enhancing the diagnosis and treatment of the condition." (PMID 40075825, 2025). "The studies discussed in the current paper support the role of elastin-derived peptides in the pathogenesis of pulmonary emphysema." (PMID 40141701, 2025). "As an extension of this approach to understanding the pathogenesis of pulmonary emphysema, the current paper proposes that the emergence of the airspace enlargement involves the dynamic interplay between mechanical strain and elastin crosslinking." (PMID 40422205, 2025). "As CELA1 is required for age-related alveolar simplification and elastin loss, it also links these 2 models to the accelerated aging model of COPD-associated emphysema." (PMID 38193533, 2024). "In macrophages, miR-93 activates the JNK pathway by targeting dual-specificity phosphatase 2, which elevates matrix metalloproteinase 9 and 12 and induces elastin degradation, leading to emphysema." (PMID 39416774, 2024). "The current model is limited to assessing only NE and PR3 footprints and does not evaluate the potential impact of cathepsin G, which has also been reported to contribute to elastin degradation, at least in a cigarette smoke-induced animal model of emphysema." (PMID 39015374, 2024). "Chymotrypsin-like elastase 1 (CELA1) is a serine protease that binds and cleaves lung elastin in a stretch-dependent manner and is required for emphysema in a murine antisense oligonucleotide model of α-1 antitrypsin (AAT) deficiency." (PMID 38193533, 2024). "In essence, proteolytic destruction of lung elastin leads to emphysema due to impaired physiological control by a suboptimal amount and function of circulating and lung AAT." (PMID 39040588, 2024). "In all 3 models, Cela1–/– mice had less emphysema and preserved lung elastin despite increased lung immune cells." (PMID 38193533, 2024). "Recent studies in our laboratory provide evidence of this phenomenon in pulmonary emphysema by relating the emergence of airspace enlargement to the release of elastin-specific desmosine and isodesmosine (DID) crosslinks from damaged elastic fibers." (PMID 38164218, 2023). "It has been suggested that macrophages produce elastolytic proteinases such as MMPs, thereby leading to the degradation of alveolar elastin and emphysema." (PMID 36771049, 2023). "In fact, emphysema is characterized by reduced elasticity of the lung; however, the alveoli walls are destroyed mainly due to the degradation of elastin fibers." (PMID 37932771, 2023). "Macrophages contribute to CS-induced emphysema development in mice, in part, by releasing Mmp-12 (which degrades lung elastin) and oxidants." (PMID 36787195, 2023). "Owing to its function, a reduced elastin content results in thinner and fragile alveolar septa to possibly effect the development of emphysema." (PMID 37932771, 2023). "NE plays a significant role in COPD progression by degrading extracellular matrix (ECM) proteins such as elastin on the release of TGF-β1, thereby damaging the alveolar structure, causing emphysema and subepithelial fibrosis." (PMID 36830984, 2023). "Isolated eosinophils obtained from the emphysema models were subjected to testing using a BODIPY-tagged elastin substrate." (PMID 37816708, 2023). "Emphysema is reported to be consequence of destroyed lung elastin and degradation of collagen matrix, presenting as the imbalance of MMPs and tissue inhibitors of MMP (TIMPs)." (PMID 35936787, 2022). "Single nucleotide variants in the 3′ end of ELN (the elastin gene) cause autosomal dominant cutis laxa (MIM #123700), which is associated with severe emphysema and characteristically lax skin." (PMID 35741248, 2022). "It has been shown that the lack and/or excessive degradation of elastin enhance the emphysema progress." (PMID 36040980, 2022).
emphysema (continued). "Elastin is critical for lung development, and Eln–/– mice display dilated distal air sac structures and emphysema, which is likely the major cause of early postnatal death." (PMID 34990407, 2022). "When the upregulating MMP-9 cannot be offset by TIMP-1 abundantly, the degradation of elastin and other extracellular matrix components occurs in the alveolar walls and finally leading to emphysema." (PMID 35936787, 2022). "Oxidative stress is recognized as an important predisposing factor in COPD pathogenesis, and MMPs are known to contribute to elastin and collagen matrix degradation, resulting in emphysema." (PMID 36290703, 2022). "Pulmonary emphysema as observed in COPD is due to elastin and collagen fiber disruption by proteases contained in PMN granules, as well as in extracellular vesicles." (PMID 35806233, 2022). "The degradation of elastin would lead to an expansion of the distal airspaces reminiscent of that seen in emphysema." (PMID 34901011, 2021). "Emphysema is a condition marked by chronic inflammation, oxidative stress, elastin damage and progressive alveolar destruction." (PMID 34537081, 2021). "In emphysema, proteolysis of elastin and other extracellular matrix (ECM) components leads to loss of elastic recoil and promotes chemoattractant activity, which perpetuates inflammatory responses and ultimately results in extensive tissue remodeling." (PMID 34136481, 2021). "Proteases, including neutrophil elastase (NE) and proteinase 3, degrade connective tissue components, especially elastin, leading to emphysema." (PMID 34681202, 2021). "Antibodies against elastin, observed in patients with emphysema, were the first evidence of a relationship between autoimmunity and COPD." (PMID 34681202, 2021). "Here we show the surprising results that mesenchyme-specific loss of Hox5 function at adult stages leads to rapid disruption of the mature elastin matrix, alveolar enlargement, and an emphysema-like phenotype." (PMID 34901011, 2021). "The level of secretion of IL-1β induced by CS extract and DEPs was higher in the elastin-induced emphysema than normal samples." (PMID 34574829, 2021). "This is our first attempt to show that local targeted delivery of pentagalloyl glucose (PGG) from nanoparticles that target degraded elastin can protect elastin damage in mild emphysema." (PMID 34537081, 2021). "However, perturbations of the elastin network of the adult lung can cause destruction of the alveolar walls that result in emphysema, and mutations in components of the elastogenesis pathway, such as tropoelastin, fibrillins and fibulins are also associated with a predisposition to emphysema." (PMID 34901011, 2021). "We demonstrate targeted delivery PGG with inhaled elastin-targeted nanoparticles in mice can arrest the effects of elastase-induced emphysema." (PMID 34537081, 2021). "Autoimmunity towards lung elastin fragments and activation of DCs have been shown to contribute to the pathogenesis of emphysema." (PMID 34271910, 2021). "Increased catalytic activity of PR3 in COPD results in a high catalytic turnover of elastin in pulmonary parenchyma in relation to impaired lung elasticity and emphysema." (PMID 34869231, 2021). "Specifically, MMP-12 and MMP-9 are more pronounced in emphysema and participate in the degradation of elastin and collagen in lung connective tissue." (PMID 34537081, 2021). "NLRP3-inflammasome expression was increased by CS extract and DEPs in both the normal and elastin-induced emphysema samples, and was suppressed by NAC." (PMID 34574829, 2021). "We are proposing an alternate pathogenesis of radiation induced pneumonitis characterized by abnormal elastin expression, emphysema and hemorrhage at successive stages interfering with epithelial repair mechanisms." (PMID 32586004, 2020). "Along with high levels of emphysema and hemorrhage, the elastin-signatures reveal a unique pathology for internal exposure." (PMID 32586004, 2020).
emphysema (continued). "On the other hand, hypoxia causes inflammatory cells such as macrophages to release the cytokines with protease activity, which results in the destruction of elastin and leads to emphysema." (PMID 32586317, 2020). "In COPD, changes in collagen subtypes I and III and elastin, interfere with the mechanical properties of the lungs, and are believed to play a pivotal role in decreased lung elasticity, during emphysema progression." (PMID 30979017, 2019). "Autoantibodies against elastin have been detected in emphysema patients, showing for the first time the presence of autoantibodies in COPD." (PMID 29422903, 2018). "In the PPE‐induced emphysema model, elastin fragments produced by PPE increase macrophage numbers, which secrete elastolytic enzymes such as MMPs." (PMID 30058137, 2018). "It is recognized that in emphysema, both elastin and collagen degradation in alveoli occurs, thus generating elastin- and collagen fragments which are released into the systemic circulation." (PMID 28103932, 2017). "An important notion of elastin research is that AAT is the main inhibitor of neutrophil elastase, and AAT deficiency leads to the development of emphysema in smokers at a relatively young age." (PMID 28103932, 2017). "Additional evidence has also confirmed the involvement of neutrophil in the degradation of elastin fibers with subsequent development of emphysema." (PMID 28860943, 2017). "Inhibition of neutrophil elastase alleviates elastin degradation and emphysema in COPD, as well as vasogenic edema and neuronal loss in acute cerebral ischemia and traumatic brain injury." (PMID 26988843, 2016). "First, elastase-induced elastin fragments are known chemokines for macrophages in an adult murine model of emphysema, and elastin fragments can impair alveologenesis." (PMID 28101062, 2016). "In adult tissue, new EF synthesis causes accumulation of dysfunctional EF present in common disorders such as emphysema, hypertension, actinic elastosis (abnormal elastin accumulation) and aortic aneurysms." (PMID 27812333, 2016). "The repetitive tissue injury is believed to increase ECM remodeling rate and shift the balance of synthesis and degradation, favoring collagen deposition in small airway walls (fibrosis) and destruction of collagens and elastin in alveolar walls (emphysema)." (PMID 27716343, 2016). "In ex vivo lungs from patients with emphysema, airspace enlargement was accompanied by an even greater increase in both elastin and collagen in the alveolar interstitium." (PMID 27138294, 2016). "To verify the dynamic alterations in some ECM components during emphysema development, we evaluated the volume proportion of types I and III collagen fibers, elastin and fibrillin at different time points following emphysema induction." (PMID 26052708, 2015). "We reasoned that deposited CSPGs inhibit the elastin recovery from airway damage also in the elastase-induced pulmonary emphysema model." (PMID 26646821, 2015). "MMP-9, produced by the activated macrophages, has the ability to cleave elastin with a majority of emphysema progressive." (PMID 26646821, 2015). "Structural changes in the ECM, including significant changes in the collagen, elastin and proteoglycan content, occur during the development of emphysema both in humans and in experimental rodent models of this disease." (PMID 26122092, 2015). "This discrepant pattern of elastin transcript and elastin fiber content has previously been identified during the early stages of animal models of emphysema." (PMID 25303643, 2014). "The role of α1-antitrypsin has been well studied in pulmonary emphysema, in which reduction of α1-antitrypin leads to destruction of elastin ECM, resulting in enlargement of alveoli." (PMID 23437119, 2013). "IL-1β and MMP-9 promote subepithelial fibrosis, subepithelial collagen deposition and elastin fibre disruption in asthma and in COPD are associated with many of the histopathological features of emphysema." (PMID 23398985, 2013).
emphysema (continued). "The preceding findings corroborate that elastin-specific Th1 and Th17 cells persist in peripheral blood of ever-smokers with emphysema." (PMID 22969766, 2012). "To confirm the presence of autoreactive elastin-specific T cells, we used freshly isolated CD4+ T cells from control and emphysema volunteers and determined the relative abundance of elastin tetramer positive T cells." (PMID 22969766, 2012). "We identify reduced elastin expression and synthesis as a possible basis of the arteriosclerosis and pulmonary emphysema of SIOD patients." (PMID 22998683, 2012). "Denny and Schroeter also examined, using 3D models, changes in tissue elasticity when the relative amount of collagen versus elastin is perturbed as happens in the early stages of emphysema." (PMID 21533072, 2011). "Recently Lee and co-workers demonstrated anti-elastin autoantibodies in patients with tobacco smoking-induced emphysema." (PMID 21162738, 2010). "Elastin is a major structural component of lung, and elastin degradation is a contributing factor to lung diseases such as emphysema and COPD." (PMID 20678199, 2010). "Proteolysis of matrix components, in particular elastin, is a major contributing factor to the development of lung diseases such as emphysema and chronic obstructive pulmonary disease (COPD)." (PMID 20678199, 2010). "Destruction of lung parenchyma in emphysema is thought to occur through excessive proteolysis mediated by the elastin-degrading enzymes MMP2, MMP9, and MMP12 from the MMP family, and by neutrophil elastase from the serine proteinase family." (PMID 15526056, 2004). "Addition of lathyrogen beta-aminopropionile leads to an impairment of collagen and elastin crosslinking and therefore further increases the extent of emphysema-like lesions." (PMID 15522115, 2004). "These emphysema-like alterations suggest that in addition to its role in the structure and function of the mature lung, elastin is essential for pulmonary development and is important for terminal airway branching." (PMID 15522115, 2004). "Given the low turnover rate of elastic fibers in healthy lungs, the DID levels in body fluids may serve as a biomarker for elastin degradation in pulmonary emphysema." (PMID 40075825, 2025). "Since the release of elastin peptides reflects a number of pathogenetic mechanisms, it may represent a point in the emergence of pulmonary emphysema where a group of agents interact concurrently to form a converging whole." (PMID 40141701, 2025). "Although many of these genetic factors remain poorly understood, their effect on elastin crosslinking and airspace distention can significantly alter the natural progression of pulmonary emphysema and limit the efficacy of treatments designed to shift the balance between injury and repair." (PMID 40422205, 2025). "Furthermore, proteases secreted by neutrophils and alveolar macrophages lead to the degradation of connective tissue and elastin at the alveolar level, with emphysema arising as a consequence of these proteolytic actions." (PMID 39851472, 2025). "Conversely, in pulmonary biopsies, our original method could analogously help identify elastin breaks in emphysema or fibrosis in idiopathic pulmonary fibrosis, differentially highlighting elastic fiber networks versus collagenous scars." (PMID 41303299, 2025). "A working hypothesis of emphysema pathogenesis is the imbalance between proteinases (that degrade structural proteins particularly elastin) and their physiologic inhibitors (i.e., antiproteinases) that prevent such destruction." (PMID 41007683, 2025). "Before the emergence of pulmonary emphysema, the fragmentation and unraveling of elastic fibers may expose the core elastin protein to enzymatic and oxidative breakdown, facilitating the release of proinflammatory peptides." (PMID 40141701, 2025). "Additionally, when PAD inhibitors are administered to mice, PAD-induced citrullination of elastin is inhibited, and the formation of emphysema is suppressed." (PMID 40565035, 2025).